ETS1 (ETS proto-oncogene 1, transcription factor)
Diseases named in the same sentence as ETS1 in open-access papers (continued):
Sharing a sentence is not in itself a finding about the gene and the disease.
cancer (continued). "Our data described here strongly suggest that in a variety of human carcinomas, over-expression of Ets1 may not just be a prognostic indicator, but play an important causal role that can be exploited for targeted therapy." (PMID 19142229, 2009). "IGF1R, one of the members of the insulin/IGF system, was mostly expressed in foetal and cancer tissues 39 and three CpG islands are predicted in the promoter region of IGF1R which may combine large list of transcript factors including MZF1, TCFL5, USF1, ETS1 and SPIB." (PMID 33085184, 2020). "Our analysis revealed that across multiple microarray and RNA-Seq based datasets, ETS1 mRNA levels were consistently high in tumors compared to normal tissues and interestingly, showed increasing expression as tumors progressed from dysplastic to carcinoma states." (PMID 31306413, 2019). "Spearman’s correlation analysis revealed a negative correlation between ETS1 and EFNA4 expression in a cohort of 407 GC samples from the TCGA Cancer Atlas." (PMID 41162582, 2025). "Snail induction by TGF‐β and active Ras is dramatically inhibited using siRNAs against both Ets1 and Ets2 together, but not on their own; in addition, siRNAs against both Ets1 and Ets2 also downregulate the constitutive expression of Snail and ZEB1/2 in cancer cells." (PMID 35451213, 2022). "Among the 5 core TFs identified in the largest TNBCac co-regulation module, ETS1 and GATA2 seemed to be not generally crucial in survival and growth of cancer cells, which may be due to nonlinear dose-dependence or insufficient shRNA interference efficiency." (PMID 28423538, 2017). "However, the literature has showed that SERPINE1 is promoted, not inhibited, by the ETS family members, such as ELK1, Ets-1 and ELK3, in other cancer types." (PMID 26335051, 2015). "The study also reveals that this inhibition occurs through the targeting of ETS1 via the PI3K/AKT/mTOR pathway and this implies that SNHG6 might act as a tumor suppressor in the context of colorectal cancer, as opposed to its oncogenic role in other cancer types." (PMID 37735423, 2023).
infection (15 papers, 2014 to 2026). The state of being infected such as from the introduction of a foreign agent such as serum, vaccine, antigenic substance or organism. "Collectively, these data indicate that the inability of VSVM51R-eGFP to deplete hSpt16SUMO results in robust ETS-1 induction during infection." (PMID 40060670, 2025). "Consistent with our microscopy results, ~37% of total ETS-1 was found in nuclear fractions of mock-infected cells, while only ~10% of ETS-1 was nuclear during VSV-eGFP infection." (PMID 40060670, 2025). "ETS-1 expression during infection is dependent upon FACT complexes that contain a specialized, SUMOylated form of hSpt16 (hSpt16SUMO)." (PMID 40060670, 2025). "Consistent with our VV studies, hSpt16 RNAi treatment abrogated ETS-1 induction after VSVM51R-eGFP infection." (PMID 40060670, 2025). "When compared to IL17RA KO mice, DKO mice develop more severe and extensive skin lesions and at a higher penetrance, indicating cooperation between Ets1 and IL17RA in regulating susceptibility to such infections." (PMID 37691956, 2023). "EMSA and DNA pull-down assay showed that BMDC infection with LDPm induced Ets1, Ets2, USF1, and USF2 binding to the mouse HAVCR2 promoter." (PMID 37202419, 2023). "The increase in HIV replication by ETS1 knockdown was enhanced when using multi-cycle HIVLAI infection." (PMID 34545078, 2021). "During HIV infection, the mRNA of ETS1 was decreased at day 3 post-infection, which corresponds to a similar trend observed for PCIF1 degradation, indicating that ETS1 was regulated by PCIF1 during HIV replication." (PMID 34545078, 2021). "Overexpression of Ets1 also reduced cell proliferation by ∼25% after 48 and 72 hrs of infection of Ets1 at two different cell density in the culture plate as detected by MTT assay." (PMID 24897113, 2014). "The divergent behavior of ETS1 with respect to HIV-1 expression at different times post infection could result from different complexes or binding partners of ETS1." (PMID 40198713, 2025). "In contrast, ~78% of ETS-1 was found in the nucleus during VSVM51R-eGFP infection." (PMID 40060670, 2025). "Interestingly, while ETS-1 protein levels were not significantly different between mock- and VSV-eGFP-infected cells, VSVM51R-eGFP-infected WCE showed significantly elevated ETS-1 by 4 h post-infection (hpi)." (PMID 40060670, 2025). "ETS-1 induction by VSVM51R-eGFP infection was unaffected in these IFN pathway knockout cell lines." (PMID 40060670, 2025). "Thus, we next used infection time courses and immunoblots (IBs) to determine if ETS-1 levels differ between VSV-eGFP and VSVM51R-eGFP infections." (PMID 40060670, 2025). "ETS2 and ETS1, evolutionarily conserved across the metazoans, are required for endothelial cell survival in mammals and play roles in anti‐infection processes in invertebrates." (PMID 40225888, 2025). "ETS1 gene was elevated upon infection by A. flavus clinical isolates." (PMID 34983375, 2022). "To determine whether cagA (a major virulence factor of H. pylori) contributes to ETS1 expression, we first carried out transwell infection assay." (PMID 32612120, 2020). "Furthermore, AGS cells infected with either H. pylori 11637 or 26695 increased ETS1 levels in an infection time- and dose-dependent manner." (PMID 32612120, 2020). "The results showed that Ets1 mRNA expression reaching a peak of 12 weeks post-infection." (PMID 32612120, 2020). "To determine whether Ets1 inhibited glucose stimulated insulin secretion (GSIS), we overexpressed Ets1 in isolated mouse islets by adenovirus-mediated infection." (PMID 24897113, 2014). "Therefore, we next asked if ETS-1 overexpression prior to infection could suppress VSV-eGFP infection." (PMID 40060670, 2025). "We also performed Co‐IP analysis using protein samples extracted from Drosophila after topical infection with M. robertsii, which revealed that glutathione S‐transferase (GST)‐tagged ETS1 and ETS6 each successfully pulled down the mature C106 ligand." (PMID 41114474, 2026).
infection (continued). "To reconcile these previous observations with our finding that ETS1 participates in repressing latent HIV-1, we examined the impact of ETS1 knockout at different timepoints post infection as well as in the presence of latency reversing agents (LRAs)." (PMID 40198713, 2025). "On the other hand, DKO mice initially started to clear the infection and on day 3 actually showed a signal that was lower than that of IL17RA KO mice and comparable to that of WT and Ets1 KO controls." (PMID 37691956, 2023). "Finally, because hSpt16SUMO is required for ETS-1 induction during ΔA51R VV infection, we wanted to determine if hSpt16 RNAi treatment would inhibit ETS-1 induction by VSVM51R-eGFP infection." (PMID 40060670, 2025). "Finally, we asked if plasmid-based expression of VSV M-Flag was sufficient to block ETS-1 induction by either VSVM51R-eGFP or ΔA51R VV infection." (PMID 40060670, 2025). "However, during VSV-eGFP infection, ETS-1, was largely excluded from the nucleus and restricted to the cytosol, suggesting that VSV infection impairs ETS-1 nuclear translocation." (PMID 40060670, 2025). "We found promising master regulators of duck genes in lung and ileum (RUNX2, SMAD3, SMAD4, and ETS1), which could be responsible for the duck’s effective differential gene expression in response to HPAI infection." (PMID 35205087, 2022). "Functional analysis of phosphoproteome and transcriptome data confirmed the involvement of these pathways in the EMT during infection, a phenotype that was confirmed in infected cells, along with the essential roles of ERK1/2, ETS1, and ERF activation in C. trachomatis replication." (PMID 35173712, 2021). "Subsequently, when HSP90B1 with GAPDHP24-induced phosphorylation further triggers the regulation of TF ETS1, HSP90B1 with ubiquitination will not activate TF ETS1 in the infection of C. albicans SC5314." (PMID 30769958, 2019). "Therefore, we wanted to determine if ETS-1 induction by VSVM51R-eGFP infection was also independent of the IFN response." (PMID 40060670, 2025). "Importantly, immunofluorescence experiments in U2OS cells also demonstrated a similar exclusion of ETS-1 from the nucleus during VSV-eGFP infections as observed in A549 cells, suggesting this was not cell type-specific." (PMID 40060670, 2025). "By focusing on genes in the DNA-binding transcription factor category of molecular functions, we identified ETS1, which we found to be regulated by PCIF1 enzymatic activity and to play an important role in HIV replication and potentially in immune cell physiology during infection." (PMID 34545078, 2021). "Notably, ETS1 levels only increased following infection with the H. pylori 11637 but not ΔcagA in AGS cells or human primary GECs." (PMID 32612120, 2020). "At 24 hr post-infection of Ad-Ets1, Ets1 did not inhibit cell proliferation, because Ets1 protein levels may not reach high levels." (PMID 24897113, 2014).
retinopathy (3 papers, 2017 to 2024). "A potent small inhibitor of ETS1 (YK-4-270) was identified recently, which reduced neovascular tufts in retinal vessels in an oxygen-induced retinopathy model." (PMID 34867089, 2021). "Dominant negative ETS1 also inhibits retinal angiogenesis during proliferative retinopathy, while antisense oligonucleotides directed against ETS1 inhibit EC migration and VEGF‐induced EC proliferation." (PMID 36795082, 2024).
adenocarcinoma (2 papers, 2015 to 2025). A common cancer characterized by the presence of malignant glandular cells. "ETS1 was not expressed in normal gastric epithelium but was expressed in 51.6% of adenocarcinomas." (PMID 41425714, 2025).
hematologic disorder (2 papers, 2011 to 2017). A disease involving the hematopoietic system. "In the current study, the cross talk among the Notch1 pathway, Ets-1, and TRPA1 in erythroid and megakaryocyte differentiation suggests a potential combinatorial strategy for treatment of hematological malignancies in the near future." (PMID 28220825, 2017).
inflammation (2 papers, 2022). Aberrant reaction of the microcirculation characterized by movement of fluid and leukocytes from the blood into extravascular tissues. "This indicated that miR-486 inhibited the expression of ETS1, which in turn promoted the synovial and joint inflammatory responses, leading to the occurrence of RA synovial inflammation and bone destruction." (PMID 36541909, 2022).
kidney diseases (2 papers, 2011 to 2023). "Pitx1, IRF3, and ETS1 are also TFs involved in the pathogenesis of kidney diseases." (PMID 36967395, 2023).
metabolic disorders (2 papers, 2024 to 2026). "Adipocyte-specific Ets1 knock-in mice are cold-intolerant, while Ets1-deficient mice exhibit enhanced energy expenditure and resistance to diet-induced metabolic disorders." (PMID 41551882, 2026). "Male adipocyte Ets1 knock-in mice are completely cold intolerant, whereas male mice lacking Ets1 in adipocytes show enhanced energy expenditure and are resistant to metabolic disorders caused by high-fat-diet." (PMID 38388532, 2024).
hematologic cancers (1 paper, 2019). "Many CIS occurred near genes implicated in hematologic cancers and hematopoietic development (Erg, Ets1, Epo, Il2rb, Flt3, Kras, Stat5b, Fli1)." (PMID 30940846, 2019).
vasculopathy (1 paper, 2022). "Furthermore, in silico analyses indicated interactions of miR-199a-5p with HIF1A, Ets-1, and TGFB2 genes, which are associated with vasculopathy and reduced NO." (PMID 35204817, 2022).
ETS1 also shares sentences with these, for which no sentence is quoted: acute myeloid leukemia (6 papers); congenital heart disease (5); celiac disease (3); allergies (2); anaplastic astrocytoma (2); angiosarcoma of the skin (2); brain neoplasm (2); childhood asthma (2); CNS tumors (2); esophageal cancer (2); follicular lymphoma (2); Hodgkins lymphoma (2); laryngeal squamous cell carcinoma (2); lymphopenia (2); metastatic prostate carcinoma (2); nasopharyngeal carcinoma (2); rhabdomyosarcoma (2); vasculitis (2); Airway obstruction (1); alopecia areata (1); anemia (1); angiosarcoma (1); Arrhythmia (1); atopic dermatitis (1); autism (1); autoimmune myocarditis (1); benign prostatic hyperplasia (1); benign thyroid tumors (1); benign tumor (1); bipolar disorder (1).
A further 62 diseases each share a sentence with ETS1 in 1 paper.